TSC1 (TSC complex subunit 1)
Diseases named in the same sentence as TSC1 in open-access papers (continued):
Sharing a sentence is not in itself a finding about the gene and the disease.
cancer (continued). "PLK1 phosphorylates TSC1 and functions as a positive upstream regulator of mTORC144,45, whereas it phosphorylates Raptor, inhibits mTORC1, and thereby induces autophagy in interphase cancer cells." (PMID 34675258, 2021). "Mutation and loss of function of TSC1 and/or TSC2 also occur in a variety of sporadic cancers, and rapamycin and related drugs show highly variable treatment benefit in patients with such cancers." (PMID 33891611, 2021). "In cancer cells harbouring these TSC2 mutations, the TSC2-NTD/TSC2-GAP, or TSC1/TSC2, or TSC2-GAP/Rheb associations may be disrupted, leading to diminished GAP activity toward Rheb and abnormally elevated mTORC1 activity." (PMID 33307091, 2021). "Inactivating TSC1 and TSC2 mutations also occur rarely in multiple cancer types." (PMID 33891611, 2021). "Furthermore, TSC1 is downregulated in several cancers, such as cancers of the breast, prostate, oral cavity, bladder, liver and lung." (PMID 33833339, 2021). "For the cancer types that performed the worst, liver hepatocellular carcinoma included none of the used oncogenes (AR, KLF4, PDGFRA, and RET) or tumor suppressors (BRCA2, CDKN2A, and TSC1) that were linked to it." (PMID 31900418, 2020). "Indeed, activation of these pathways due to the loss of their negative regulators, tuberous sclerosis complex 1 and 2 (Tsc1 and Tsc2) and phosphatase and tensin homolog (PTEN), respectively, can cause cancer." (PMID 29677182, 2018). "TSC1 or TSC2 dysfunction is also implicated in uncontrolled growth and cancer." (PMID 28632179, 2017). "These TSC1/TSC2 loss of function mutations activate mammalian target of rapamycin (mTOR) protein kinases, which promote both cell proliferation and survival, have been implicated in various types of cancer." (PMID 27377753, 2016). "As in fibroblasts, GSK3 modulates TSC1/TSC2 complex via phosphorylation mechanisms in cancer cells." (PMID 25273085, 2014). "The significance of these complex biochemical signaling events is that cancer cells that overexpress activated Akt or lack PTEN/TSC1/TSC2 expression have an Achilles heel with regards to therapeutic intervention as they are highly sensitive to rapamycin treatment." (PMID 23006971, 2012). "Since effusions are characterized as clusters of detached carcinoma cells, the parallel dysregulation of TSC1 and ezrin expression may play a critical role in effusion formation." (PMID 19680458, 2010). "Further, as cancer cells with hyperactive mTORC1, either due to loss of PTEN or TSC1/2, have been shown to be particularly sensitive to rapamycin treatment, we speculate that cancer cells with mutated NPRL2 might also be particularly sensitive to rapamycin." (PMID 19521502, 2009). "In addition, gain of function of CXXC5 induced inhibition of target genes, such as TSC1, and regulated the mTOR pathway positively, which could regulate the expression of PD-L1 in cancer cells." (PMID 36539038, 2023). "Notably, of the eight cancer-related genes, six (TSC1, TSC2, PIK3CA, IGF1R, PDPK1 and AKT2) are known longevity related genes according to GenAge database in human/model organisms, and genetic manipulation of these genes can directly lead to shortening or extending lifespan of model organisms." (PMID 37582720, 2023). "Moreover, mutations of FBWX7, ERBB2, TET2, BCL2L1, NOTCH1, FGFR1 and TSC1 were only detected in patients without germline cancer-associated variants." (PMID 30850667, 2019). "Besides miR-17 target genes altered during early-stage cancer include TSC1 and HEXIM1." (PMID 31756185, 2019). "Pan-cancer (pan-cancer/NSCLC models; cross-indication) evidence suggests enhanced ICI sensitivity with TSC1/2 alterations, informing mTOR- and ICI-based strategies." (PMID 41154602, 2025). "However, it remains unclear whether null alleles of TSC1 in humans may result in a phenotype that generates several types of malignant tumors, potentially in the absence of more classic clinical manifestations of TSC." (PMID 38802873, 2024).
cancer (continued). "Here, we describe a novel multiprotein complex (DockTOR) essential for the survival of cancer cells under stress, triggered by the GTPase Cdc42 and a signaling partner Dock7, which includes AKT, mTOR, and the mTOR regulators TSC1, TSC2, and Rheb." (PMID 36711811, 2024). "We subsequently investigated the correlations between the CNV of ISCA1 and the RNA expression of FRGs and reported that the ISCA1 CNV was positively correlated with TSC1, FXN, BRD3, and MAPKAP1 in most cancer types." (PMID 39766805, 2024). "In contrast, its overexpression increases phosphorylation and activity of both TSC1 and TSC2, whereas increased phosphorylation of S6K1 and 4E-BP1 is observed in DYRK1A knockdown cancer cells—the effect inhibited by the mTOR-inhibiting drug rapamycin." (PMID 36982355, 2023). "qRT-PCR was performed to detect the relative expression levels of TSC1, ITGA6, and MET in normal and cancer cell lines." (PMID 36261830, 2022). "The results indicated that the expression levels of TSC1, ITGA6, and MET in most cancer cell lines (SW1990, PANC1, Mia-paca-2, CFPAC1) were significantly higher than those in the normal cell line (H6C7)." (PMID 36261830, 2022). "AKT activation leads to cell growth by activating mTOR through TSC1/2 phosphorylation, while increased levels of TSC1/TSC2 inhibit the mTOR pathway; mTOR positively regulates 4E-BP1 and p70S6k, which are activated in a variety of cancers." (PMID 33805447, 2021). "Due to the dysregulation of upstream tumor suppressors or oncogenes, such as PTEN, TSC1/2, PI3K, or IRS1, AKT/mTOR signaling is frequently activated in various cancers." (PMID 33204686, 2020). "No variants were evident in the key cancer genes PTEN, MTOR, AKT1, TSC1/2 or MDM2, or in genes encoding components of PI3K." (PMID 37079639, 2023). "Indeed, in one study, cancer cell lines treated with TNFα activate IKKβ, a component of the IKK complex that interacts with and phosphorylates TSC1, resulting in TSC1 inhibition and mTORC1 activation." (PMID 37628917, 2023). "Moreover, TSC1/mTOR was found to control RIPK3-dependent necroptosis in intestinal inflammation and cancer." (PMID 38161978, 2023). "Gadd45g expression was significantly upregulated in stellate cells and cancer cells when miR-301a was inhibited, whereas Tsc1 expression was not altered." (PMID 35211358, 2022). "In addition to known cancer driver genes such as ERBB2 (6% of cases), NRAS (3%), MET (3%), PIK3CA (1%), AKT2 (1%), TSC1 (1%), and ERBB4 (1%), several putative cancer genes were identified, such as PTPRC, SYNE2, GRIN2A, and CDH10." (PMID 24576404, 2014). "However, the clinical implications of genetic variations in TSC1 or TSC2 in cancer patients have not yet been elucidated." (PMID 30842342, 2019). "However, overexpression of CDK4 did not affect the mRNA levels of TSC1 in these cancer cells." (PMID 38890443, 2024).
genetic disorder (44 papers, 2007 to 2026). "Tuberous sclerosis complex (TSC) is a genetic disorder caused by mutations in either the TSC1 or TSC2 genes." (PMID 41255962, 2025). "TSC is a genetic disorder with an incidence of 1 in 6000 people worldwide caused by mutations in the TSC1 or TSC2 genes." (PMID 38255309, 2024). "Tuberous sclerosis complex (TSC) is a genetic disorder marked by the formation of multiple benign tumors arising from mutations in TSC1 or TSC2 genes." (PMID 38570425, 2024). "Although TSC is a genetic disease, TSC1/2 mutations are inherited only 30% of the time, with 70–90% cases inheriting a TSC2 mutation." (PMID 38802873, 2024). "TSC, which stems from Tsc1 or Tsc2 mutations, is another genetic disorder with pronounced ASD comorbidities." (PMID 38139124, 2023). "Tuberous sclerosis (TSC) is a genetic disorder caused by mutation of the TSC1 or TSC2 genes, encoding two crucial proteins: TSC1 (hamartin) and TSC2 (tuberin)." (PMID 36430972, 2022). "Tuberous sclerosis complex (TSC) is a multisystem genetic disorder caused by pathogenic variants in TSC1 and TSC2 genes." (PMID 36238691, 2022). "Tuberous sclerosis complex (TSC) is a multiorgan genetic disease inherited in an autosomal dominant way through a mutation of the TSC1 or TSC2 gene." (PMID 35956179, 2022). "Tuberous sclerosis complex (TSC) is an inherited genetic disorder characterized by mutations in TSC1 or TSC2 class of tumor suppressers which impact several organs including the kidney." (PMID 35814396, 2022). "Tuberous sclerosis complex (TSC) is a genetic disorder caused by inactivating mutations in TSC1 (hamartin) or TSC2 (tuberin), crucial negative regulators of the mechanistic target of rapamycin complex 1 (mTORC1) signaling pathway." (PMID 33923449, 2021). "Tuberous sclerosis complex (TSC) is a genetic disorder that is caused in part by loss‐of‐function mutations in one of two genes, TSC1 or TSC2." (PMID 33786950, 2021). "Tuberous sclerosis complex (TSC) is a genetic disease affecting 1:6000–1:13,000 newborns, caused by a mutation in one of two loci: TSC1 located on chromosome 9q34.13) or TSC2 (located on chromosome 16p13.3)." (PMID 34884198, 2021). "Tuberous sclerosis complex (TSC) is a genetic disease caused by mutations in the TSC1 and TSC2 genes." (PMID 27042238, 2016). "Tuberous sclerosis complex (TSC) is a genetic disorder caused by heterozygous inactivating mutations of either the TSC1 or TSC2 gene." (PMID 26693177, 2015). "Tuberous sclerosis complex (TSC) is a genetic disease resulting from mutation in TSC1 or TSC2 and subsequent hyperactivation of mammalian Target of Rapamycin (mTOR)." (PMID 26220190, 2015). "Tuberous sclerosis complex (TSC) is a genetic disorder resulting from a mutation of either the TSC1 gene on chromosome 9q34 or the TSC2 gene on chromosome 16p13." (PMID 24822087, 2014). "Tuberous sclerosis complex (TSC) is a genetic disorder characterized by multi-system hamartomas, which occur from mutations of the TSC1/TSC2 genes and subsequent overactivation of the mammalian target of rapamycin (mTOR) signaling pathway and dysregulation of cell proliferation." (PMID 36467422, 2022). "Furthermore, patients with the genetic disorder tuberous sclerosis complex (TSC) (mutations in the TSC1 or TSC2 gene), commonly develop tumors like astrocytomas or angiomyolipomas as well as the related lung disorder Lymphangioleiomyomatosis (LAM)." (PMID 30764584, 2019). "Tuberous sclerosis complex (TSC) is a multisystem genetic disorder that results from a mutation in the TSC1 or TSC2 genes leading to constitutive activation of mammalian target of rapamycin complex 1 (mTORC1) and is therefore highly associated with intractable epilepsy." (PMID 27122151, 2016). "This rare, multisystem genetic disease results from mutations from one of two genes, TSC1 or TSC2." (PMID 26998374, 2016).
genetic disorder (continued). "Mutations in the TSC1 and TSC2 genes lead to dysfunctional mTOR signaling and cause tuberous sclerosis complex (TSC), a genetic disorder that affects multiple organ systems, principally the brain, heart, skin, and kidneys." (PMID 38534508, 2024). "TSC1 and TSC2 genes were named because some of their mutations are related to a genetic disorder TSC." (PMID 37990318, 2023). "TSC1 and TSC2 genes are mutated in a genetic disorder called tuberous sclerosis complex (TSC)." (PMID 28353628, 2017). "In terms of treatability, TSC1-, TSC2-, SLC35A2-, ATP7A-, ALDH7A1-, and MMACHC-related disorders had specific therapeutic regimens and accounted for 18.5% (19/103) of the cases with genetic disorders." (PMID 35330882, 2022).
benign tumors (24 papers, 2012 to 2025). "Germline mutations in TSC1 or TSC2 genes cause benign tumors in multiple organs in patients with TSC." (PMID 29491408, 2018). "In TSC, the growth of benign tumors in various organs occurs from loss of TSC1 or TSC2 genes and subsequent overactivation of mammalian target of rapamycin (mTOR), a kinase responsible for regulating cell growth, proliferation, and angiogenesis." (PMID 27351628, 2016). "In TSC patients, germ line and somatic dominant loss of function mutations in the genes encoding hamartin (TSC1) or tuberin (TSC2) can cause the development of benign tumors and, abnormally differentiated cortical neuronal progenitors that may cause focal seizures." (PMID 30761153, 2019). "The primary cause of TSC is mutations in the TSC1 (hamartin) or TSC2 (tuberin) genes, leading to dysregulation of the mTOR signaling pathway and the formation of benign tumors." (PMID 40364023, 2025). "Tuberous sclerosis complex is an autosomal dominant disorder characterized by benign tumors arising from the abnormal activation of mTOR signaling in cells lacking TSC1 (hamartin) or TSC2 (tuberin) activity." (PMID 29343513, 2018).
neurodevelopmental disorder (15 papers, 2016 to 2026). A behavioral and cognitive disorder with onset during the developmental period that involves impaired or aberrant development of intellectual, motor, or social functions. "Tuberous sclerosis complex (TSC) is a neurodevelopmental disorder with epileptic seizures caused by genetic mutations in either TSC1 or TSC2 gene." (PMID 41484896, 2026). "Tuberous sclerosis complex (TSC) is a neurodevelopmental disorder caused by mutations in the TSC1 and TSC2 genes and autosomal dominantly inherited." (PMID 35241183, 2022). "Tuberous sclerosis complex (TSC) is a neurodevelopmental disorder caused by deletions in the TSC1 or TSC2 genes that is associated with epilepsy in up to 90% of patients." (PMID 31761686, 2019). "Tuberous Sclerosis Complex (TSC) is a neurodevelopmental disorder caused by mutations in TSC1 or TSC2, which encode proteins that negatively regulate mTOR complex 1 (mTORC1)." (PMID 31780742, 2019). "TSC is a neurodevelopmental disorder caused by mutations in the TSC1 or TSC2 genes." (PMID 38419709, 2024). "Its knockdown in Xenopus causes nuclear breakdown, apoptosis, and a striking loss of tissue architecture in the neural tube, but its associations with neurodevelopmental disorders, with which Disc-1 or TSC1 have linkages, are still unknown." (PMID 28125008, 2017). "Tuberous Sclerosis Complex (TSC) is a neurodevelopmental disorder arising primarily from mutations in TSC1 (hamartin) and TSC2 (tuberin) (TSC1/2)." (PMID 35241183, 2022). "Genes implicated in ASD such as Annexin 1 (ANXA1), HLA-B and CNTN6 with deletion or duplication in a spectrum of neurodevelopmental disorders and ID were upregulated in TSC1-Het and Null NPCS when compared with the WT." (PMID 31921404, 2020).
infection (14 papers, 2012 to 2025). The state of being infected such as from the introduction of a foreign agent such as serum, vaccine, antigenic substance or organism. "In vivo studies showed that loss of TSC1 function can lead to the apoptosis of T cells and remarkably suppress the infection-specific immune responses of T cells." (PMID 34243823, 2021). "Although we have associated miR-126 with tsc1 and the cxcl12a/ccl2/ccr2 axis by combinatorial gene depletion studies, miR-126 has been documented to be involved in additional pathways that may impact the outcome of infection." (PMID 38307625, 2024). "Statistically significant reduction of bacterial burden was observed in both lungs and spleens from TSC1f/f LysM-Cre+ mice 3 weeks post-infection compared to WT mice, suggesting that greater autophagy induction in TSC1 deficient macrophages may cause killing of infecting bacilli." (PMID 27387347, 2016). "In cultured MLO-Y4 cells, infection of TSC1 shRNA lentivirus significantly induced Sirt1 expression and accelerated Sost promoter H3K9 acetylation, while rapamycin treatment reduced Sirt1 levels." (PMID 31088250, 2019). "Infection of the TSC1 KO macrophages with M. tuberculosis strain H37Rv further increased the phosphorylation of p70S6K and the accumulation of LC3B-II and p62." (PMID 27387347, 2016). "Activation of mTOR signaling pathway by either leucine stimulation, Ad-S6K1 infection or TSC1 knockdown all reverses the inhibition effect of ghrelin on Th17 cells." (PMID 25658305, 2015). "Taken together, our results indicate that HCMV-infection activates AMPK which in turn is necessary for the induction of TSC1 and Glut4 levels." (PMID 22291597, 2012). "Furthermore, delivery of shRNA sequences targeting Tsc1 resulted in sustained reduction of protein levels up to one year post infection." (PMID 26046460, 2015). "Similar to the observation with AMPK inhibition, treatment with STO-609 also blocked the increases in TSC1 and Glut4 levels observed during HCMV-infection." (PMID 22291597, 2012). "At last, we compared the difference of T-bet expression between Lck-mTOR mice and Lck-TSC1 mice under the same infection degree (MSS group) and found that in the same MSS group, Lck-mTOR mice had more T-bet expression than WT mice, while Lck-TSC1 mice had less expression than WT mice." (PMID 32431684, 2020). "To investigate whether TSC1-mTOR signaling is essential for V. vulnificus-induced M1 polarization, we infected the WT and TSC1 KO BMMφs with two multiplicity of infection (MOI) of V. vulnificus pretreated with or without rapamycin." (PMID 33585271, 2020). "In the absence of infection, the percentage and number of Tregs in TSC1 KO mice was higher than that in WT mice, suggesting that constitutive mTORC1 activity may induce more Tregs." (PMID 27746591, 2016).
autosomal dominant disease (7 papers, 2012 to 2026). Autosomal dominant form of disease. "Tuberous sclerosis complex (TSC) is an autosomal dominant inherited disorder (incidence: 1: 6,000–1:10,000 live births) resulting from pathogenic variants in TSC1 or TSC2 and leading to hamartomatous lesions in various organs." (PMID 41528496, 2026). "LAM can occur either sporadically or concomitantly in patients with tuberous sclerosis complex (TSC), an autosomal dominant disease caused by TSC1/TSC2 gene inactivation." (PMID 36117164, 2022). "Tuberous sclerosis complex (TSC) is a rare autosomal dominant disease caused by the mutation in the TSC1 gene or TSC2 gene." (PMID 34243823, 2021). "Tuberous sclerosis complex (TSC) is a rare, autosomal dominant disease of variable penetrance, which results from mutations in the genes TSC1 (which codes for hamartin) or TSC2 (which codes for tuberin), respectively." (PMID 34344419, 2021). "TSC is an autosomal dominant disease with an estimated incidence of 1 in 5800 at birth and is caused by loss-of-function mutations of the TSC1 or TSC2 gene." (PMID 29423330, 2018). "TSC is an autosomal dominant disease that is associated with gene mutations of TSC1 or TSC2, encoding hamartin and tuberin, respectively." (PMID 23072249, 2012).